FLCN (folliculin)
Diseases named in the same sentence as FLCN in open-access papers (continued):
Sharing a sentence is not in itself a finding about the gene and the disease.
oncocytoma (10 papers, 2014 to 2025). "BHD syndrome, a rare autosomal dominant disorder caused by the folliculin gene alterations, provides important insights into oncocytoma biology." (PMID 40770850, 2025). "Patient 1, with a germline FLCN mutation and a history of BHD syndrome, presented with a well-circumscribed oncocytic adenoma." (PMID 40277780, 2025). "Mutations in the tumor suppressor FLCN are associated with multiple histological subtypes of RCC, such as chromophobe, clear cell, oncocytoma, and hybrid oncocytic." (PMID 39352796, 2024). "The high-grade oncocytic carcinoma region showed decreased protein expression of FLCN when compared with the benign oncocytoma-like regions." (PMID 25275525, 2014). "As such, our global transcriptomic analysis revealed an even more aggressive phenotype for the high-grade oncocytic carcinoma region than that of HOT “hybrid chromophobe-oncocytomas” of BHDS mediated by FLCN." (PMID 25275525, 2014). "In summary, the findings are consistent with an FLCN-driven oncocytic adenoma." (PMID 40277780, 2025). "We began this study with a case of oncocytic adenoma in a BHD patient harboring a biallelic oncogenic FLCN mutation, with no other oncogenic alterations detected by routine RNA or DNA sequencing." (PMID 40277780, 2025). "Germline mutations in the tumor suppressor FLCN cause Birt-Hogg-Dubé (BHD) syndrome, which is characterized by benign skin lesions, pulmonary cysts, spontaneous pneumothorax, as well as chromophobe, clear cell, oncocytoma, and hybrid oncocytic RCC." (PMID 39352796, 2024). "Herein, we found that the prevalence of BAP1, FLCN, and MITF p.E318K alterations in this cohort was 6.2% (5 of 81 patients, after excluding benign renal neoplasia, such as oncocytoma and angiomyolipoma; 95% CI 2.3%-14.5%) (eFigure in the Supplement)." (PMID 34767027, 2021). "Likely germline alterations of BAP1, FLCN, and MITF were identified in 6.2% of cases after excluding benign renal neoplasia (oncocytoma and angiomyolipoma)." (PMID 34767027, 2021). "There could be defects or dysregulation at any part of the folliculin/FNIP1-mTOR-TFEB axis that prevented the biogenesis of lysosome, as seen with oncocytoma." (PMID 40806782, 2025). "Moreover, we found that the prevalence of BAP1, FLCN, and MITF p.E318K alterations in this cohort was 6.2% (5 of 81 patients, after excluding benign renal neoplasia, such as oncocytoma and angiomyolipoma; 95% CI 2.3%-14.5%)." (PMID 34767027, 2021).
colorectal cancer (9 papers, 2011 to 2024). A primary or metastatic malignant neoplasm that affects the colon or rectum. "In rare cases, patients have also been reported to have colorectal cancer, salivary gland oncocytomas, melanomas, oral papules, and thyroid cancers, although it remains unclear whether FLCN variants are responsible for these manifestations." (PMID 38963008, 2024). "BHD may predispose patients to colorectal cancer because of folliculin’s role in AMPK/AKT/mTOR signaling and its inhibition of LDHA, synergizing with the more familiar APC pathway through established intermediaries of cell growth." (PMID 36859772, 2023). "Furthermore, the risk for colorectal cancer might be slightly increased in FLCN mutation carriers." (PMID 22146830, 2011). "Besides, it was reported that the frameshift mutations in the FLCN exon 11 which would suppress the activation of FLCN could lead to the increased incidence of colorectal cancer." (PMID 35154239, 2021).
breast carcinoma (8 papers, 2017 to 2025). "In luminal breast cancer, the loss of FLCN activates TFE3, which then induces pathways promoting tumor growth, such as autophagy, lysosome biogenesis, aerobic glycolysis, and angiogenesis." (PMID 40143966, 2025). "The calcineurin regulatory subunit PPP3R1 shows elevated expression in ER− breast cancer, whereas positive regulators of Rag C/D, including folliculin complex members FLCN and FNIP1, along with MAP4K3, are decreased in ER− breast cancer patients." (PMID 36372230, 2022). "Professor Leeanna found that FLCN, FNIP1, and FNIP2 are downregulated in various human cancers, particularly in poorly prognostic invasive basal-like breast cancer, as opposed to luminal, less aggressive subtypes." (PMID 40143966, 2025).
melanoma (7 papers, 2017 to 2026). A malignant, usually aggressive tumor composed of atypical, neoplastic melanocytes. "Additionally, eight individuals with pathogenic FLCN variants developed malignant melanoma." (PMID 41193855, 2026). "This matched cohort study of 353 Swedish born individuals with P/LP variants in FLCN confirms an increased risk of both CRC and malignant melanoma in patients with BHDS." (PMID 41193855, 2026). "We first looked at an extended list of high-risk genes predisposing to melanoma (ACD, CDKN2A, CDK4, POT1, TERF2IP, and TERT) or RCC (CDKN2B, FH, FLCN, MET, PBRM1, PTEN, SDHs, TSCs, and VHL) or both (BAP1 and MITF)." (PMID 34067022, 2021). "An additional five cases displayed clinically pathogenic variant in three genes predisposing to either melanoma or RCC, namely FLCN (N = 2), CDKN2A (N = 2), and PTEN (N = 1)." (PMID 34067022, 2021). "In contrast, none of the 7 participants with FH or FLCN mutations were reported to have clinical indicators of HLRCC or BHD syndrome and none of the 10 carriers of P MITF variants had a past history of melanoma." (PMID 35441217, 2022).
primary spontaneous pneumothorax (7 papers, 2008 to 2025). "We think that the causes underlying the molecular mechanism of familial spontaneous pneumothorax can be discovered through the examination of the connection between mutations in different exons of the FLCN and familial spontaneous pneumothorax." (PMID 31625278, 2019). "To determine whether folliculin sequence variants are risk factors for severe COPD, we genotyped seven previously reported Birt-Hogg-Dubé or familial spontaneous pneumothorax associated folliculin mutations in 152 severe COPD probands participating in the Boston Early-Onset COPD Study." (PMID 19116017, 2008). "Considering the previous studies, no definite distinction has been found between the type of FLCN mutation, BHD syndrome, and familial spontaneous pneumothorax." (PMID 31625278, 2019).
colon carcinoma (6 papers, 2011 to 2025). "To confirm that the hanging drop results were FLCN-dependent and not cell-type specific to the UOK cells, we grew T84 colon carcinoma cells stably expressing non-targeting or FLCN shRNA in adherence-free conditions using a rotary shaker." (PMID 23139756, 2012).
cystic lung disease (6 papers, 2012 to 2024). "It suggests that mutation analysis of the FLCN gene should be systematically conducted in patients with cystic lung diseases." (PMID 28558743, 2017). "Our results suggest that mutation analysis of the FLCN gene should be systematically conducted in patients with cystic lung diseases." (PMID 28558743, 2017). "Molecular analysis of the FLCN gene should be systematically conducted in patients with cystic lung diseases in such cases." (PMID 32631372, 2020). "Despite these advances, the molecular functions of FLCN and the cellular mechanisms through which BHD mutations lead to renal and skin tumorigenesis and cystic lung disease are incompletely understood." (PMID 23139756, 2012). "We hypothesize that FLCN‐dependent effects on signaling and cellular adhesion contribute to the pathogenesis of cystic lung disease in BHD patients." (PMID 25121506, 2014). "Dysregulation of the FLCN-p0071 interaction may underlie the unusual triad of lung, skin, and renal manifestations in BHD patients, and could have critical implications for the pathogenesis of cystic lung disease and chromophobe renal cell carcinoma in the general population." (PMID 23139756, 2012).
polycystic kidneys (6 papers, 2008 to 2024). "As functional partners of FLCN, double inactivation of FNIP1/2 in murine kidney produces enlarged polycystic kidneys similar to FLCN deficiency." (PMID 33981707, 2021). "In a mice model (FLCN FLOX/FLOX/Ksp‐Cre), specific knockout of FLCN in renal distal tubule and collecting duct cells leads to polycystic kidney disease and uremia, resulting in death within 3 weeks of birth." (PMID 38963008, 2024). "Further studies using organ-specific Flcn knockout mice demonstrated characteristic disorders such as polycystic kidney disease, cardiac hypertrophy and alveolar enlargement, indicating that FLCN function is involved in a wide variety of human disorders." (PMID 29720200, 2018). "Before investigating the correlation of FLCN with mTOR pathway, we first examined the distribution of FLCN in normal mouse kidney and polycystic kidney." (PMID 18974783, 2008). "In the polycystic kidney, FLCN was only detected in relatively normal tubules, which are mainly proximal tubules." (PMID 18974783, 2008). "Similarly, kidney specific FLCN knockout or FLCN heterozygous knockout mice develop enlarged polycystic kidneys with pre-neoplastic lesions." (PMID 33981707, 2021).
Clear cell renal cell carcinoma (5 papers, 2013 to 2025). "Clear cell renal cell carcinoma exhibits certain molecular genetic characteristics, and molecular genetics can detect genes such as Von Hippel-Lindau (VHL), folliculin (FLCN), and BRCA1-associated protein-1(BPA1)." (PMID 40395268, 2025). "We first detected the protein levels of FLCN in normal renal tubular epithelial cells and clear cell renal cell carcinoma by Western blotting." (PMID 32850947, 2020). "Here we explored whether there is connection between VHL and FLCN in clear cell renal carcinoma cell lines and tumors." (PMID 23922894, 2013). "Among these cases, one had renal clear cell carcinoma with unilateral cystic lesions and negative folliculin (FLCN) genetic testing." (PMID 39934870, 2025). "Aims and Hypothesis: This study aims to explore the specific molecular mechanism of folliculin (FLCN)-induced proliferation, migration, and invasion in clear cell renal cell carcinoma (ccRCC) and to investigate the relationship of FLCN and HIF2α." (PMID 32850947, 2020).
Kidney Cyst (5 papers, 2017 to 2021). Abnormal fluid filled sac within the kidney, either acquired or congenital. "Germ line mutations in FLCN are responsible for the autosomal dominant inherited disorder Birt–Hogg–Dubé (BHD) syndrome which presents lung and kidney cysts and kidney cancer." (PMID 33924874, 2021).
lung carcinoma (5 papers, 2013 to 2025). "We herein present a novel FLCN mutation-mediated case of BHD complicated by primary lung cancer and review the pertinent literature." (PMID 40630489, 2025). "It is unclear whether the FLCN mutation contributes to the KRAS mutation in lung cancer." (PMID 40630489, 2025). "This case highlights the complexities of managing lung cancer in BHD patients and suggests a potential role for FLCN mutations in tumorigenesis." (PMID 40630489, 2025). "In our case, the patient has lung cancer with BHD syndrome, and a previously unreported FLCN mutation was detected at chr17:17129575–17129591 in exon 5 (c.295_311del p.Asp99Ter)." (PMID 40630489, 2025). "To explore the molecular mechanism of paclitaxel induced autophagy in FLCN-deficient cells, we examined the alteration of the ERK pathway, which is known to be associated with autophagic regulation in lung cancer cells." (PMID 24305604, 2013). "Therefore, the present data should be interpreted with caution regarding whether the patients with germline FLCN mutations have an increased risk of developing lung cancer compared to individuals without this genetic disorder." (PMID 26974543, 2016).
chromophobe renal cell carcinoma (4 papers, 2020 to 2025). Chromophobe renal cell carcinoma is a rare subtype of renal cell carcinoma, originating from the intercalating cells of the collecting ducts and macroscopically manifesting as a well-circumscribed, highly lobulated, solid tumor that is usually diagnosed at an early stage. "A 44-year-old female with BHD syndrome (confirmed via FLCN germline mutation) and a history of multifocal chromophobe renal-cell carcinoma presented with a newly detected thyroid nodule on routine physical exam." (PMID 40277780, 2025). "Birt-Hogg-Dubé (BHD) syndrome, caused by germline alteration of folliculin (FLCN) gene, develops hybrid oncocytic/chromophobe tumour (HOCT) and chromophobe renal cell carcinoma (ChRCC), whereas sporadic ChRCC does not harbor FLCN alteration." (PMID 37182269, 2023).
Obesity (4 papers, 2021 to 2024). Accumulation of substantial excess body fat. "FLCN deficiency in WAT protects mice from diet-induced obesity and increases resistance to cold exposure." (PMID 33981707, 2021). "Overweight and obesity are complex conditions modulated by several causes, so we designed a multifactorial model to predict BMI taking into consideration the relevance of genetic susceptibility of the FLCN-FNIP complex investigated herein." (PMID 36316722, 2022). "Loss of FLCN leads to AMPK-dependent increase in autophagy, HIF-1/2 activity, and resistance to obesity, energy stress, osmotic stress, and pathogens." (PMID 33981707, 2021). "A similar effect of obesity was detected in mRNA for Slc38a9, an amino acid (arginine) sensor on lysosomes which aides in mTORC1 regulation, and disassembly of the lysosomal-folliculin complex allowing FLCN GAP activation of RagC." (PMID 38166559, 2024). "Collectively, these results provide evidence that rs2291007-FNIP2-Folliculin complex could modulate overweight and obesity." (PMID 36316722, 2022). "Such molecules would represent new possibilities for treatment of obesity and NASH through the role of FLCN in hepatocyte homeostasis." (PMID 34711912, 2021).
thyroid cancer (4 papers, 2014 to 2025). "By characterizing the clinical, histologic, and genetic profiles of these two FLCN-mutated thyroid neoplasms and examining the broader role of FLCN alterations in thyroid carcinoma pathogenesis, we seek to expand the understanding of the genetic landscape of thyroid tumors." (PMID 40277780, 2025). "Indeed, in FLCN-deficient thyroid cancer FTC-133 cells, dysregulation of RAB7 activity due to loss of FLCN determined slower EGFR degradation, increased EGFR signaling, and tumor growth." (PMID 31374919, 2019). "In the publicly available databases, a total of 2062 patients with thyroid carcinoma had FLCN gene coverage and met the inclusion criteria." (PMID 40277780, 2025). "In this dataset, 1091 patients with thyroid carcinoma were identified with FLCN gene coverage by NGS." (PMID 40277780, 2025). "Thyroid carcinomas are driven by diverse molecular alterations, but the tumor suppressor gene folliculin (FLCN), best known for its role in Birt–Hogg–Dubé (BHD) syndrome, has received limited attention in thyroid tumors." (PMID 40277780, 2025). "Here, we describe two thyroid tumors with pathogenic FLCN alterations—one germline and one somatic—and analyze the broader prevalence and significance of FLCN in thyroid carcinomas using multiple large sequencing datasets, including ORIEN-AVATAR." (PMID 40277780, 2025). "To further investigate the incidence and clinical relevance of FLCN alterations in thyroid carcinomas, we analyzed data from multiple large publicly available sequencing databases, as well as the ORIEN-AVATAR dataset." (PMID 40277780, 2025). "In the datasets analyzed, oncogenic FLCN alterations appear to be rare events in thyroid carcinoma, occurring in a total of 35 out of 3153 (1.1%) unique patients." (PMID 40277780, 2025). "In this study, we present the first comprehensive analysis of FLCN gene alterations in thyroid carcinomas, including both germline and somatic settings." (PMID 40277780, 2025). "Further studies are needed to clarify FLCN’s role in thyroid cancer pathogenesis." (PMID 40277780, 2025). "Thyroid carcinomas revealed FLCN alterations in 1.1% of cases." (PMID 40277780, 2025). "Furthermore, secondary FLCN alterations were frequently encountered in aggressive thyroid tumors lacking oncocytic morphology, highlighting the complexity of FLCN’s role in thyroid tumorigenesis and underscoring the need for its inclusion in clinical molecular panels for thyroid cancer diagnostics." (PMID 40277780, 2025). "In contrast, secondary FLCN alterations are more commonly seen in aggressive thyroid carcinomas, where they may not result in an oncocytic histology." (PMID 40277780, 2025).
tuberous sclerosis (4 papers, 2012 to 2024). Hereditary disease characterized by seizures, intellectual disability, developmental delay, and skin and ocular lesions. "Tuberous sclerosis (TSC) is a tumour suppressor gene syndrome and its clinical similarities to that of BHD suggest that the FLCN and TSC proteins may function in a common cellular pathway." (PMID 29744825, 2019). "Moreover, in the renal tumours from mouse models of tuberous sclerosis complex (TSC), the absence of Tsc2 inhibits FLCN and thus promotes RagC/DGTP formation, establishing a non‐canonical means of preventing mTORC1‐mediated phosphorylation of TFEB, thereby driving its nuclear translocation." (PMID 37728021, 2023).
Hornstein-Knickenberg syndrome (3 papers, 2020 to 2023). "Birt–Hogg–Dubé syndrome (BHDS), which is also called Hornstein-Knickenberg syndrome (HKS), is a hereditary autosomal dominant disorder caused by germline mutations in the folliculin gene (FLCN, NM_144997)." (PMID 33240319, 2020).
lung disease (3 papers, 2020 to 2022). "Three patients without a FLCN pathogenic variant had two cysts each and were not suspected to have another underlying lung disease." (PMID 36028846, 2022).
PEComas (3 papers, 2016 to 2025). "Regarding molecular characteristics, PEComas are characterized by mutations leading to mTOR pathway activation, such as TSC1 or TSC2 bi-allelic inactivation, TFE3 gene fusion and FLCN truncating mutations." (PMID 34680376, 2021). "Explaining the mutual exclusivity between TSC1/2 inactivation and MiT/TFE gene rearrangements in PEComas, we and others have previously shown that mTORC1 activation leads to constitutive activation of TFEB and TFE3 through FLCN inactivation." (PMID 41044182, 2025).
pulmonary neoplasm (3 papers, 2016 to 2025). "An additional subject of future study is whether somatic mutation or deletion of FLCN is observed in a subset of sporadic lung neoplasms." (PMID 26974543, 2016). "Collective data indicated that pulmonary neoplasms of peripheral adenocarcinomatous lineage in BHD patients frequently exhibit LOH of FLCN with mTOR pathway signaling." (PMID 26974543, 2016). "It is tempting to hypothesize that LOH of FLCN, concomitant with oncogenic mutations in EGFR or KRAS, might allow low-grade lung neoplasms to progress to invasive adenocarcinomas." (PMID 26974543, 2016). "Therefore, the somatic state of FLCN and the expression level of FLCN in lung neoplasms appear to be somewhat different from those in RCC." (PMID 26974543, 2016). "Additionally, no pulmonary neoplasm has been reported to date that was proved to have complete loss-of-function type FLCN mutation, hence meeting the Knudson’s 2-hit theory." (PMID 27871249, 2016). "Not only invasive adenocarcinomas but also noninvasive neoplasms showed FLCN LOH, which indicates that the somatic event alone may not be sufficient for pulmonary neoplasms to transform to an aggressive phenotype." (PMID 26974543, 2016).